COMT (catechol-O-methyltransferase)
Diseases named in the same sentence as COMT in open-access papers (continued):
Sharing a sentence is not in itself a finding about the gene and the disease.
mental disorder (18 papers, 2010 to 2025). A disease that has its basis in the disruption of mental process. "As changes in the dopamine system are thought to play a major role in the development of psychiatric diseases, functional dopamine-associated variations in the 22q11 chromosome, such as COMT Val105/158Met, are strong candidates for exploring the genetic components of mental disorders." (PMID 35741850, 2022). "The COMT gene, coding for the enzyme catechol-O-methyltransferase, responsible for dopamine and norepinephrine inactivation, is one of the prominent candidate genes for susceptibility to mental disorders located in this interval, and is considered a major candidate gene in OCD." (PMID 20565924, 2010). "Catechol O-methyltransferase (COMT, OMIM: 116790) gene (located on human chromosome 22q11) has been studied in several mental disorders associated with SCZ." (PMID 27843998, 2015). "Beyond ADHD, the role of COMT is investigated in conjunction with many other mental disorders." (PMID 30108607, 2018). "Accordingly, one or several removed genes in the regions of COMT may be involved in their mental disorders." (PMID 27843998, 2015). "Therefore, one further possible explanation for the association between COMT, social impairment, and ADHD might be that the association is not specific for ADHD but associated with a possible general impact resulting from mental disorders." (PMID 30108607, 2018). "And hub proteins, such as POMC, COMT, NPS, BDNF, also have the potential to be applied as targets for the diagnosis and treatment of mental disorders." (PMID 27917343, 2016). "Early-life stress may also impact methylation of other genes related to the pathophysiology of various mental disorders, such as BDNF, COMT, MAOA, FKBP5, and SLC6A4." (PMID 33284958, 2021). "Furthermore, it was found that hub proteins, such as COMT, POMC, NPS and BDNF, might be the potential targets for mental disorders therapy." (PMID 27917343, 2016).
22q11.2 deletion syndrome (17 papers, 2006 to 2025). 22q11.2 deletion syndrome (DS) is a chromosomal anomaly which causes a congenital malformation disorder whose common features include cardiac defects, palatal anomalies, facial dysmorphism, developmental delay and immune deficiency. "AMPT has been tested in clinical trials of 22q11.2 deletion syndrome (which is characteristic of COMT polymorphism)." (PMID 39063020, 2024). "Studies on the association between COMT and psychopathy-related behaviors were replicated in a sample with autism spectrum disorder and a sample with 22q11.2 deletion syndrome." (PMID 35163702, 2022). "Here we found that extreme COMT reduction, in both humans (22q11.2 deletion syndrome COMT Met) and mice (COMT−/−), was associated to cortical thinning only after puberty and only in females." (PMID 28556830, 2017). "Therefore, further work is needed to assess comprehensively the possible relation between hemizygosity of 22q11.2 deletion, long-term COMT deficiency, and clinical presentations in chromosome 22q11.2 deletion syndrome." (PMID 27017469, 2016). "The effect of COMT genotype on brain activation in Velocardiofacial syndrome has been found to be moderated by sex." (PMID 33221753, 2020). "Note that ARVCF (Armadillo Repeat gene deletes in Velocardiofacial syndrome, GeneID 421) is adjacent to COMT on chromosome 22, so it is included in the GRAIL gene set." (PMID 20102619, 2010). "22q11 proximal deletion, also known as DiGeorge syndrome or velocardiofacial syndrome, involves more than 30 Mendelian genes; potential genes such as TBX1, COMT, UFD1L, GNB1L, TRXR2, MED15, and RANBP1 were researched to explore the phenotype/CNV correlation." (PMID 32863884, 2020). "With regards to the neurobehavioral features seen in 22q11.2 deletion syndrome, the roles of COMT (catechol-O-methyltransferase) and PRODH (proline dehydrogenase) have been investigated, given their relevance to dopaminergic and glutamatergic neurotransmission, respectively." (PMID 35046931, 2021).
alcoholism (17 papers, 2011 to 2025). "In alcoholism, a genetic background of COMT appears to play a significant role in causing such increased plasma HVA concentrations." (PMID 32678220, 2020). "Variability of the COMT activity has previously been associated with the Val158Met polymorphism of the COMT gene and alcoholism." (PMID 24878765, 2014). "Additionally, one study found sex-specific associations for high-activity COMT and alcohol dependence, seen in male alcohol dependent participants only." (PMID 33364985, 2020). "Such complexity in different patterns of moderation effect elaborated the partial effect of COMT activity on alcoholism suggested by prior study in other Asian population." (PMID 40857241, 2025). "Catechol-O-methyltransferase (COMT) functional polymorphism, Val158Met, has been associated with alcoholism in Caucasians." (PMID 30011860, 2018). "Since COMT plays a crucial role in the metabolism of dopamine it is likely that it contributes to the etiology of alcohol dependence." (PMID 22208661, 2011). "The aim of this study was to assess the relationship between the severity of craving for alcohol and COMT polymorphisms DRD2 genes and traits of temperament and character, as well as selected clinical and anthropometric factors in patients with alcohol dependence." (PMID 34945190, 2021). "Moreover, variations in genes encoding catechol-o-methyltransferase (COMT), one of the enzymes responsible for the degradation of catecholamines, are associated with alcohol dependence." (PMID 33266373, 2020). "The influence of BDNF and COMT on neurocognition in alcohol dependence is unclear." (PMID 23087644, 2012). "Genome-wide association studies of nicotine and alcohol dependence have not found association with COMT to date." (PMID 22208661, 2011). "However there have been conflicting studies for COMT including a study that did not observe association with alcohol dependence or nicotine dependence." (PMID 22208661, 2011).
Hypertension (17 papers, 2008 to 2024). The presence of chronic increased pressure in the systemic arterial system. "Ang II infusion in null COMT female mice indicates higher blood pressure suggesting that loss of estradiol metabolism pathway is detrimental during hypertension." (PMID 35586713, 2022). "Catechol-O-methyltransferase (COMT) which degrades dopamine, epinephrine, and norepinephrine to 3-methoxytyramine is inhibited by mercury and cadmium and causes hypertension, probably due to the increase in epinephrine and norepinephrine concentrations." (PMID 33535566, 2021). "Several small population-based studies found genetic variation in COMT to be associated with coronary heart disease and hypertension in men." (PMID 30011860, 2018). "There is a well-established association between the COMT Val108/158Met polymorphism and abdominal obesity and blood pressure increase, human hypertension, and T2DM." (PMID 29225702, 2017). "The Chi square analysis for the association of COMT polymorphism (I/D) with family history of diabetes, nephropathy and hypertension was also performed." (PMID 25969822, 2015). "COMT genotypes related to sex, mean age, education > 12 years, mean systolic and diastolic blood pressure, and several factors associated with hypertension." (PMID 18578865, 2008). "COMT knockout mice may be better suited to study the impact of COMT deficiency in the development of hypertension and hypertension during pregnancy." (PMID 34276401, 2021). "COMT Val158Met homozygosity for the low-activity allele (Met/Met), has been associated with myocardial infarction (ncases = 69, ncontrols = 723) and metabolic disorders like abdominal obesity and high blood pressure in men (n = 240)." (PMID 30045690, 2018). "In COMT-null mice, 2ME2 downregulated Ang II receptors expression in the aorta and reduced Ang II-induced hypertension corroborates our findings in the kidney and liver." (PMID 35586713, 2022). "There are previous reports demonstrating a relationship between COMT Val158Met and acute coronary events, ischemic stroke and CVD risk factors like hypertension and lipid abnormalities." (PMID 30045690, 2018). "Hagen and coworkers reported that high COMT activity (Val/Val genotype) is overrepresented in male and female Norwegians with systolic hypertension (≥140 mmHg) (n = 2591)." (PMID 30045690, 2018). "COMT is a candidate gene for hypertension since degradation of catecholamines plays a critical role in the regulation of vessel tone and blood pressure." (PMID 26973509, 2016). "It is therefore necessary to explore the use of resveratrol in an animal model that exhibits hypertension during pregnancy, particularly since it increases uterine artery blood flow velocity in the COMT−/− mice." (PMID 23667712, 2013). "Previous studies have indicated the antibacterial potential of the anticancer drug Tirapazamine and Tolcapone—a catechol-O-methyltransferase inhibitor used in the symptomatic management of idiopathic Parkinson’s disease and hypertension treatment—except against species other than P. aeruginosa." (PMID 39061324, 2024). "A significant correlation between COMT gene polymorphism in CAD cases with respect to T2D but not hypertension was also found." (PMID 30011860, 2018). "The catechol-O-methyltransferase-gene-disrupted mice were resistant to salt-induced hypertension." (PMID 26821914, 2016). "In addition, pharmacological inhibition of COMT produces arterial hypertension and endothelial dysfunction in pregnant rats which may be attributed to reduced NO bioavailability." (PMID 30237900, 2018). "AgII-induced hypertension was ameliorated both by 2-ME and AMPK activators, indicating the close relationship between COMT and AMPK." (PMID 30304773, 2018).
anxiety disorder (16 papers, 2005 to 2025). A category of psychiatric disorders which are characterized by anxious feelings or fear often accompanied by physical symptoms associated with anxiety. "This frequency of Met allele carriers is consistent with other studies of the COMT Val158Met polymorphism and anxiety disorders." (PMID 23596403, 2013). "Variation in the COMT gene has been implicated in a number of psychiatric disorders, including psychotic, affective and anxiety disorders." (PMID 16232322, 2005). "The COMT SNP G472A (rs4680) has been widely associated with various neuropsychological phenotypes from the dopaminergic pathway, including pain modulation, hyperalgesia, anxiety disorders, opioid-related disorders, and substance addiction." (PMID 36422103, 2022). "Since anxiety disorders have been associated with oxytocin system alterations, it could be speculated that the COMT effects are related to OT system specificities in these patients." (PMID 23554586, 2013). "The role of Catechol-O-Methyltransferase (COMT) in dopamine metabolism has led to investigation of its variants in the etiology of numerous psychiatric disorders including psychotic, affective and anxiety disorders." (PMID 16232322, 2005). "The relationship between COMT Val158Met and physiological fear conditioning paradigms is beginning to be examined also in healthy adults and adults with anxiety disorders and posttraumatic stress disorder (PTSD)." (PMID 26395975, 2016). "A recent study has shown that 5-HTTLPR and COMT modulated the vulnerability for anxiety disorders via different mechanisms." (PMID 26418317, 2015). "Previous studies imply that the abnormality of certain genes is associated with anxiety disorders, such as CRHR1, FKBP5, CREB, Egr-1, Glo1, Gsr, AC8, CaMKIV, dystrophin, HTTLPR and COMT Met158." (PMID 22681774, 2012). "Indeed, there is an increasing number of reports that central DA markers, including the DA transporter, the DA degrading enzyme COMT, D1 and D2 receptors, are abnormal in patients with an anxiety disorder or PTSD." (PMID 38191458, 2024). "These actions were shown to modulate crucial target proteins, including SLC6A4, COMT, and MAOA, thereby exhibiting a significant therapeutic impact on anxiety disorders." (PMID 38684743, 2024).
preeclampsia (15 papers, 2011 to 2025). Preeclampsia is a hypertensive disorder of pregnancy that is characterized by new-onset hypertension with proteinuria presenting after 20 weeks of gestation, and depending on mild or severe forms may initially present with severe headache, visual disturbances, and hyperreflexia. "Catechol-O-Methyltransferase (COMT), an enzyme responsible for degrading catecholamines and catechol estrogens, has been implicated in preeclampsia pathogenesis." (PMID 40004721, 2025). "Functional polymorphisms in human COMT can result in reduced enzymatic activity at physiological temperatures, contributing to fetal growth restriction and other complications of preeclampsia." (PMID 40004721, 2025). "COMT-deficient mice exhibit a preeclampsia-like phenotype characterized by placental hypoxia, increased nuclear HIF-1α levels in the placenta, and elevated circulating sFlt-1." (PMID 40004721, 2025). "Regarding the physiological significance of 2ME, deficiency in 2ME and COMT leads to a preeclampsia-like phenotype in mice and shows anti-inflammatory properties in vivo and in vitro." (PMID 32498358, 2020). "COMT deficiency is a shared molecular mechanism between preeclampsia, metabolic syndrome and type II diabetes." (PMID 32498358, 2020). "Our single SNP analysis showed no significant results, but haplotype analysis revealed a significant association between COMT and preeclampsia." (PMID 21304959, 2011). "Epidemiologic data has consistently demonstrated a strong genetic susceptibility to preeclampsia and COMT has been identified as a candidate gene for preeclampsia studies." (PMID 21304959, 2011). "Our findings have demonstrated both protective and risk alleles for COMT in association with the risk for preeclampsia." (PMID 21304959, 2011). "In our study, the ATCA haplotype of COMT increased the risk for preeclampsia when the fetus also carried a low activity allele of the MTHFR gene, characterized by the minor “T” allele at SNP rs1801133." (PMID 21304959, 2011). "The potential for MTHFR to influence risk for preeclampsia both through a single gene effect and an interaction with COMT was studied." (PMID 21304959, 2011). "In the present case-control study, we investigated the association between COMT haplotypes and preeclampsia in 1,103 Chilean maternal-fetal dyads." (PMID 21304959, 2011). "Based on previous findings of haplotype-specific differences in enzymatic activity and protein levels, we evaluated the relationship of the functional variation linked to COMT haplotype and preeclampsia." (PMID 21304959, 2011). "This significant association between COMT and preeclampsia highlights the importance of this gene in preeclampsia, but does not support the causative mechanism suggested by the Comt knock out mouse." (PMID 21304959, 2011). "The results of our current study showed that a maternal haplotype of COMT, which likely results in decreased levels of maternal 2-ME production, was in fact protective and decreased the risk for preeclampsia." (PMID 21304959, 2011). "Logistic regression model of primary risk factors for preeclampsia including COMT haplotype specified according to reported enzymatic activity." (PMID 21304959, 2011). "Although our results appear consistent with the mouse model, further studies are needed to understand how COMT behaves differently in the maternal and fetal compartments to modulate the risk for preeclampsia." (PMID 21304959, 2011). "Low fetal COMT expression, as observed in Patient 1, could create an added risk during vascular development and gestation and has been associated with preeclampsia and sudden infant death syndrome (SIDS)." (PMID 31111659, 2019). "COMT deficiency could be the shared molecular mechanism between preeclampsia, the metabolic syndrome and type 2 diabetes." (PMID 28801594, 2017).
preeclampsia (continued). "Here, we hypothesized that COMT deficiency is a shared pathogenesis in the onset of the metabolic defects observed in the metabolic syndrome, type 2 diabetes, and preeclampsia." (PMID 28801594, 2017). "The potential for COMT to contribute to preeclampsia risk through maternal BMI led us to investigate whether the association between maternal COMT haplotype and preeclampsia risk in our study could be explained by a relationship between COMT and BMI." (PMID 21304959, 2011). "Thus, the protective maternal effect of COMT on the risk for preeclampsia is likely the result of a translational mechanism." (PMID 21304959, 2011). "Moreover, severe preeclampsia and fetal growth restriction have been associated with reduced placental COMT activity." (PMID 21304959, 2011). "In the present study, we found that the maternal ACCG haplotype of COMT, which is associated with low enzyme activity, was associated with a significantly reduced risk for preeclampsia in this population, and that the risk increased in a linear fashion from low to high activity alleles." (PMID 21304959, 2011). "Second, we focused on 2-ME as a functional methoxy-catechol via COMT similar to the COMT-preeclampsia theory; however, it is possible that COMT deficiency under high fat diet feeding conditions could be associated with a wide variety of functional-methoxycatechols defects." (PMID 28801594, 2017). "We speculate that decreased maternal COMT activity would be beneficial by increasing the production of 2-ME by the placenta and that a placental loss of COMT activity is the key deficiency that contributes to the development of preeclampsia." (PMID 21304959, 2011). "Although effective, hydralazine has been shown to inhibit placental COMT activity, potentially exacerbating preeclampsia by reducing 2-ME levels." (PMID 40004721, 2025). "Various murine models have interrogated the role of hypoxia in development of preeclampsia, including mice overexpressing HIF1A and mice deficient in catechol-O-methyltransferase that produce the HIF1A inhibitor 2-methoxyestradiol." (PMID 36227697, 2022). "Another protein that is associated with angiotensin-mediated inflammatory response and preeclampsia is catechol O-methyltransferase (COMT), which was found to be increased 1.5-fold in SD-PE." (PMID 33969702, 2021). "Various factors including endoglin, endothelin, catechol-O-methyltransferase, or angiotensin-II are likely involved in endothelial dysfunction in pregnant or preeclampsia condition." (PMID 29311569, 2018). "The concentration of maternal 2ME in the circulation immediately increases during normal pregnancy; however, the levels of COMT and 2ME are significantly lower in women with severe preeclampsia." (PMID 26000015, 2015). "In fetal samples, we found that the fetal ATCA COMT haplotype and the fetal MTHFR minor “T” allele interact to increase preeclampsia risk (p = 0.022)." (PMID 21304959, 2011). "When considering the COMT gene independently, our results show that the maternal low activity haplotype of COMT, ACCG, was associated with a significantly lower risk for preeclampsia." (PMID 21304959, 2011). "In contrast, an interaction between a fetal haplotype of COMT and fetal MTHFR, which likely results in decreased level of fetal 2-ME production; increased the risk for preeclampsia as was initially predicted." (PMID 21304959, 2011). "We tested for association between COMT haplotypes and the MTHFR 677 C→T polymorphism and preeclampsia risk in 1103 Chilean maternal-fetal dyads." (PMID 21304959, 2011). "Our findings demonstrate a role for both maternal and fetal COMT in preeclampsia and highlight the importance of including allelic variation in MTHFR." (PMID 21304959, 2011). "A significant interaction (P = 0.022) between the fetal ATCA COMT haplotype and the fetal MTHFR was observed, which resulted in an increased risk for preeclampsia (OR = 1.370; 95% CI: 1.048, 1.792)." (PMID 21304959, 2011).